RN7SL428P (RNA, 7SL, cytoplasmic 428, pseudogene)
Gene: Miscellaneous RNA gene on chromosome 15 (85,210,053 to 85,210,299, reverse strand). Ensembl gene ENSG00000277582.
Homologues: Orthologues: chimpanzee Metazoa_SRP (80% identical), macaque Metazoa_SRP (36% identical), macaque Metazoa_SRP (32% identical). Paralogues in human: Metazoa_SRP (100% identical), RN7SL331P (100% identical), RN7SL417P (70% identical), RN7SL736P (68% identical), RN7SL214P (68% identical), RN7SL319P (68% identical), Metazoa_SRP (66% identical), RN7SL241P (66% identical), RN7SL536P (65% identical), Metazoa_SRP (65% identical), RN7SL106P (65% identical), RN7SL209P (65% identical), and 707 more.